IGF2BP2 (insulin like growth factor 2 mRNA binding protein 2)
Diseases named in the same sentence as IGF2BP2 in open-access papers (continued):
Sharing a sentence is not in itself a finding about the gene and the disease.
diabetes (continued). "The aim of this study was to evaluate the association of alternative variations within IGF2BP2 gene with GADA negative diabetes in Malaysian subjects." (PMID 23029108, 2012). "We aimed to characterise the possible longitudinal associations of common diabetes-susceptibility variants in the KCNJ11, PPARG, TCF7L2, IGF2BP2, CDKAL1, SLC30A8 and HHEX gene loci, with fasting glucose level; and of an obesity-associated variant in the FTO gene, with body mass index (BMI)." (PMID 20929593, 2010). "IGF2BP2 alternative variants were associated with GADA negative diabetes." (PMID 23029108, 2012). "IGF2BP2 can be activated by mTOR and promotes its binding to IGF2 mRNA of IGF2 thereby leading to diabetes mellitus." (PMID 29736175, 2018). "Thus, IGF2BP2 may causally affect diabetes but not through BMI." (PMID 32366963, 2020). "The associations of 23 SNPs located within 17 candidate genes (MTHFR, PPARγ, LPL, INSIG, TCF7L2, FTO, KCNJ11, JAZF1, CDKN2A/B, ADIPOQ, WFS1, CDKAL1, IGF2BP2, KCNQ1, MTNR1B, IRS1, ACE) with overweight and obesity, diabetes, metabolic phenotypes, and MetS were examined in both studies." (PMID 24959828, 2014). "The association of IGF2BP2 alternative variants; rs7651090, rs16860234 and rs6777038 with GADA negative diabetes was evaluated in Malaysian subjects." (PMID 23029108, 2012). "The aim of this study was to evaluate the association of alternative variants of IGF2BP2; rs6777038, rs16860234 and rs7651090 with glutamic acid decarboxylase antibodies (GADA) negative diabetes in Malaysian Subjects." (PMID 23029108, 2012). "However, due to the lack of information about diabetes mellitus status in our oral cancer patient group, the relationships between IGF2BP2 SNPs and diabetes mellitus in oral cancer patients should be further addressed in the future." (PMID 32784624, 2020). "A combination study of genomic and transcriptomic analysis presented a positive correlation between the circulating transcript of IGF2BP2 and fasting insulin in individuals without diabetes, suggesting that IGF2BP2 might take part in the pathophysiology of T2DM before the onset of the disease." (PMID 36891946, 2023).
hepatocellular carcinoma (43 papers, 2009 to 2026). A malignant tumor that arises from hepatocytes. "Another study found that IGF2BP2 expression was associated with tumor progression in glioblastomas and hepatomas." (PMID 34239534, 2021). "MiR-216b is implicated in the pathogenesis and progression of hepatocellular carcinoma through regulating IGF2BP2 and HBX36." (PMID 33824282, 2021). "In fact, before its identification as an m6A reader, IGF2BP2 had already suggested to be associated with tumor progression through preserving the stemness phenotype in glioblastoma and hepatocellular carcinoma." (PMID 31230592, 2019). "Despite these findings, the role of IGF2BP2 in the specific pathogenesis of HBV‐associated hepatocellular carcinoma (HCC) remains poorly understood." (PMID 40900809, 2025). "LINC00665 can modulate 11 mRNAs by regulating m6A enzymes YTHDF1, IGF2BP1, and IGF2BP2 in hepatocellular carcinoma (HCC)." (PMID 38351139, 2024). "Another study showed that METTL3 catalyzes m6A modification of FEN1 mRNA, which is recognized and stabilized by IGF2BP2 in hepatocellular carcinoma cells." (PMID 35502895, 2022). "For example, high expression of IGF2BP2 in hepatocellular carcinoma can promote cell migration and invasion abilities by activating the Wnt/β-catenin pathway." (PMID 35717493, 2022). "To determine which reader proteins mediate the mRNA stability of Gys2, we independently depleted the six candidate readers in Hepa 1-6 (mouse hepatocellular carcinoma) cells and found that depletion of only IGF2BP2 reduced Gys2 mRNA expression." (PMID 36396934, 2022). "Autoantibodies to IGF2BP2 has been detected in different cancers including hepatocellular carcinoma." (PMID 19832977, 2009). "IGF2BP2 has been identified as a key regulator of stem-like, tumorigenic properties in hepatocellular carcinoma (HCC), glioblastoma, osteosarcoma, CRC, acute myeloid leukemia (AML), and other cancers." (PMID 39596216, 2024). "Thus, targeting IGF2BP2 could be a promising therapeutic strategy for hepatocellular carcinoma." (PMID 38443392, 2024). "On the other hand, it has been reported that LncRNA miR4458HG binds to m6A reader IGF2BP to promote the stability of IGF2BP2-mediated target mRNA (HK2), thereby altering the physiology of human hepatocellular carcinoma." (PMID 38180752, 2024). "METTL14/IGF2BP2 prevents m6A-modified lncRNA ARHGAP5-AS1 degradation, playing an important part in hepatocellular carcinoma growth and metastasis." (PMID 37280679, 2023). "IGF2BP2 was proved to act as an oncogene, and maintained FEN1 expression through an m6A- dependent mechanism in hepatocellular carcinoma cells." (PMID 36358640, 2022). "In hepatocellular carcinoma, IGF2BP2 directly recognizes and binds to the m6A site of the FEN1 mRNA, increased the stability of FEN1 mRNA, and promotes the proliferation of hepatocellular carcinoma cells." (PMID 35299748, 2022). "Additionally, IGF2BP2 enhances the expression of the lncRNA TRPC7-AS1, which in turn upregulates HMGA2 expression, driving hepatocellular carcinoma progression." (PMID 39596216, 2024). "For example, the SE-driven m6A readers IGF2BP2/3 stabilise DDX21 mRNA to facilitate the progression of acute myeloid leukaemia, and the SE-regulated lncRNA LINC01089 induces alternative splicing of DIAPH3 through m6A modification to drive hepatocellular carcinoma progression." (PMID 41436435, 2025). "Moreover, autoantibodies to IGF2BP2 were detected in the serum of some hepatocellular carcinoma patients but not in precancerous lesions like chronic hepatitis or liver cirrhosis hepatitis." (PMID 37280679, 2023). "In a follow-up dataset analysis involving individuals diagnosed with cirrhosis (GSE15654), it was observed that patients with hepatocellular carcinoma (HCC) exhibited significantly higher levels of IGF2BP2 expression compared to those without HCC." (PMID 38443347, 2024).
glioblastoma (42 papers, 2016 to 2025). The most malignant astrocytic tumor (WHO grade IV). "We identified a set of SNP-lincRNA-RBP (164:G >C - SNHG25 – IGF2BP2) that are all highly associated with glioblastoma multiforme and potentially involved in the regulatory network related to m6A methylation." (PMID 41387767, 2025). "Collectively, IGF2BP2 in glioblastoma is linked to the regulation of cell migration and invasion through the modulation of these key proteins." (PMID 38398118, 2024). "CLIP data suggested binding to RNAs associated with mitochondrial respiration and IGF2BP2 was demonstrated to localize complex I RNA targets to mitochondria in glioblastoma cells." (PMID 37248468, 2023). "In addition, IGF2BP2 is a m6A methylation reader and is associated with prognosis in glioblastoma patients." (PMID 41387767, 2025). "Insulin like growth factor 2 mRNA binding protein 2 (IGF2BP2) has five targets in SNHG25 identified in the glioblastoma multiforme cell line (MGG8) and one target inside the disrupted region." (PMID 41387767, 2025). "The differential expression of SNHG25 and IGF2BP2 suggests their biological function in glioblastoma multiforme." (PMID 41387767, 2025). "An example is the structural change in the lincRNA small nucleolar RNA host gene 25 (SNHG25), which overlaps the binding site of protein insulin like growth factor 2 mRNA binding protein 2 (IGF2BP2) in glioblastoma multiforme." (PMID 41387767, 2025). "A binding site of RBP IGF2BP2 was observed in this disrupted region in a glioblastoma cell line, and the IGF2BP2 gene is also up-regulated in glioblastoma multiforme." (PMID 41387767, 2025). "IGF2BP1, IGF2BP2 and IGF2BP3 are dysregulated in many tumor types, being associated with chemoresistance in glioblastoma, ovarian and colorectal cancer." (PMID 40061896, 2025). "Repression of IGF2BP2 inhibited cell viability, cell proliferation, metastases, drug‐resistance, and tumor‐forming capacity in glioblastoma." (PMID 39783247, 2025). "The predicted structural change in lincRNA SNHG25 holds a potential insight into the mechanism of protein IGF2BP2 in recognizing RNA methylation signals in glioblastoma multiforme." (PMID 41387767, 2025). "In glioblastoma, IGF2BP2 binds to oxidative phosphorylation-related mRNAs, such as NDUFS3 and COX7b, delivering them to mitochondrial polysomes for translation." (PMID 39596216, 2024). "IGF2BP2 exhibits elevated expression in glioblastoma, where it plays a role in governing the migratory and invasive capabilities of the cells." (PMID 38398118, 2024). "Another study showed that IGF2BP2 maintains glioblastoma stem cell properties by mediating the silencing of a let-7 target gene." (PMID 37936610, 2023). "A further study demonstrated that IGF2BP2 stabilises CASC9 to accelerate aerobic glycolysis in glioblastoma." (PMID 37444417, 2023). "IGF2BP2 has been shown to regulate oxidative phosphorylation in glioblastoma, with shRNA silencing of IGFBP2 reducing the oxygen consumption rate and inhibiting tumour sphere formation." (PMID 37444417, 2023). "One of those family members, IGF2BP2, was previously shown to have an important role in maintaining oxidative phosphorylation and clonogenicity in glioblastoma cells." (PMID 35104504, 2022). "This study aims to investigate the mechanism underlying IGF2 mRNA-binding protein 2 (IGF2BP2) and long noncoding RNA DANCR in etoposide resistance of glioblastoma (GBM) cells." (PMID 35141227, 2021). "For example, overexpression of IGF2BP2 enhances proliferation, invasion, and metastasis of glioblastoma multiforme cells." (PMID 35011587, 2021). "In glioblastoma cells, it has also been shown that Igf2bp2 can protect let-7 target molecules from being silenced by this miRNA, suggesting a new mechanism of regulation for maintaining the NSC state." (PMID 31963852, 2020).
glioblastoma (continued). "In in vitro 2-D and 3-D cultures of glioblastoma cancer stem cells (CSCs), IGF2BP2 is capable of binding to the mRNAs of 400 genes, which are overrepresented with genes regulating mitochondrial function and oxidative phosphorylation (OXPHOS)." (PMID 29736175, 2018). "In glioblastoma cells, IGF2BP2 facilitates the trafficking of mRNAs to the vicinity of mitochondria for subsequent translation and cellular functions." (PMID 29736175, 2018). "These include IGF2, LAMB2, LIMS2, TRIM54, and hundreds of transcripts immunoprecipitated with IGF2BP2 ribonucleoprotein complexes from gliomaspheres formed by glioblastoma stem cells." (PMID 29736175, 2018). "IGF2BP2 is overexpressed in glioblastoma compared to the normal adult brain, and its increase correlates with a poor prognosis in the proneural glioblastoma subtype, which is refractory to current therapy." (PMID 29736175, 2018). "Previous in vitro study using glioblastoma cell lines suggests that IGF2BP2 promotes glioblastoma cell proliferation and invasion and facilitates their epithelial-mesenchymal transition." (PMID 29736175, 2018). "In the past few years, more experimental evidence has linked IGF2BP2 to the progression of cancer, including HCC, glioblastoma, and breast, ovarian, colon, and esophageal cancer, particularly the maintenance of cancer stem cells." (PMID 29736175, 2018). "Among the mRNAs immunoprecipitated with IGF2BP2 ribonucleoprotein complexes in gliomaspheres formed by glioblastoma stem cells, genes regulating mitochondrial function and oxidative phosphorylation are significantly overrepresented." (PMID 29736175, 2018). "The expression of HMGA2 and IGF2BP2 increased in seven established glioblastoma cell lines after anti-Let-7 treatment." (PMID 27102443, 2016). "And the expression of IGF2BP2 is positively related with the poor prognosis of glioblastoma." (PMID 39783247, 2025). "Finally, NOL4 and IGF2BP2 are instead directly involved in the maintenance of Glioblastoma Stem Cells." (PMID 40507925, 2025). "In addition, both the lincRNA SNHG25 and the RBP IGF2BP2 are up-regulated in glioblastoma multiforme according to the annotation from lncRNAfunc." (PMID 41387767, 2025). "We infer that SNHG25 is likely to function by binding with IGF2BP2 in glioblastoma multiforme." (PMID 41387767, 2025). "In addition, IGF2BP2 induces chemoresistance in glioblastoma cells and lncRNA GAS5 represses gliomas stemness and malignancy." (PMID 39417309, 2025). "Notably, IGF2BP2 protects the target genes of the let-7 miRNA family from silencing, helping to maintain glioblastoma stem cell populations." (PMID 39596216, 2024). "Notably, the binding of the lncRNA HIF1A-AS2 to IGF2BP2 supports the adaptation of glioblastoma multiforme stem cells to hypoxia." (PMID 39596216, 2024). "This IGF2BP2/DANCR-mediated suppression of FOXO1 led to etoposide resistance in glioblastoma cells." (PMID 38328550, 2024). "Furthermore, IGF2BP2 is linked to tumor growth and poor outcome in other cancer types, such as HCC, gallbladder cancer, pancreatic cancer, and glioblastoma." (PMID 37248468, 2023). "Additionally, IGF2BP2 has been shown to influence the oxidative phosphorylation (OXPHOS) in glioblastoma cancer stem cells." (PMID 37248468, 2023). "Furthermore, the two m6A sites of PDZ binding kinase (PBK) are regulated by SRSF7 in glioblastoma cells through recognition by IGF2BP2." (PMID 35625706, 2022). "Likewise, it was interrelated to insulin-like growth factor-2 mRNA-binding protein 2 and ATP-dependent RNA helicase A, whereby endorsing the self-renewal and growth of mesenchymal glioblastoma stem-like cells in hypoxic conditions." (PMID 35285425, 2022). "Similarly, a study revealed that insulin-like growth factor 2 mRNA-binding protein 2 (Imp2) regulates oxidative phosphorylation (OXPHOS) in primary glioblastoma GSC spheres (gliomasphere)." (PMID 34885110, 2021).
glioblastoma (continued). "A similar function of IGF2BP2 in stemness maintenance may also exist under pathological conditions; deletion of IGF2BP2 gene in glioblastoma stem cells impairs their clonogenecity." (PMID 29736175, 2018). "Furthermore, IGF2BP2 also could interfere with miRNA repression in some cancer cells including glioblastoma, colorectal, and thyroid cancer." (PMID 34226535, 2021). "Future biomolecular experiments are warranted to study the precise position in IGF2BP2 that SNHG25 (both wild-type and mutant) binds to and the impacts of this binding on recognizing m6A-modified mRNAs in glioblastoma multiforme." (PMID 41387767, 2025). "In glioblastoma multiforme, HIF1A-AS2 acts as a protein scaffold facilitating interactions with co-partners IGF2BP2 and DHX9, leading to the maintenance of mesenchymal glioblastoma stem-like cells in hypoxic niches by activating HMGA1 expression." (PMID 38920249, 2024). "On the contrary, lncRNA OIP5 antisense RNA 1 (OIP5-AS1) interferes with miR129-5p mediated IGF2BP2 suppression, resulting in increased IGF2BP2 expression and temozolomide (TMZ) resistance in glioblastoma cells." (PMID 38328550, 2024). "For example, in glioblastoma stem cells, m6A-modified MYC is recognized by YTHDF2, while in acute myeloid leukemia, it is recognized by IGF2BP2." (PMID 38879589, 2024). "For instance, HIF1A-AS2 promotes the expression of HMGA1 through interactions with IGF2BP2 and DHX9, aiding glioblastoma stem-like cells (GSCs) in adapting to hypoxia within the tumor microenvironment." (PMID 39416790, 2024). "Intriguingly, SRSF7 has been demonstrated to be a novel m6A regulator, which exerts a tumorigenic effect in glioblastoma via its modulation of m6A sites on PDZ-binding kinase, and via binding by the m6A reader IGF2BP2." (PMID 37444417, 2023). "In glioblastoma, IGF2BP2 recognizes the m6A site of lncRNA CASC9 and increases its stability, and CASC9 cooperates with IGF2BP2 to form a complex that stabilizes hexokinase 2 (HK2), promoting aerobic glycolysis." (PMID 35541906, 2022). "IGF2BP2 also inhibits the phosphotyrosine interaction domain containing 1 (PID1) expression through the DANCR/FOXO1 axis, leading to drug resistance in glioblastoma cells and promoting glioma progression." (PMID 35625706, 2022). "Igf2bp2 is a target of HMGA2 in different cell types; it is an mRNA binding protein also involved in stem cell maintenance in glioblastoma, a neural tumor in which HMGA2 is reactivated." (PMID 31963852, 2020). "It will be valuable to screen all proteins that bind with SNHG25 in glioblastoma to study whether SNHG25 interacts with IGF2BP2 and promotes the formation of a complex including SNHG25, IGF2BP2 and other proteins." (PMID 41387767, 2025). "In addition, elevated levels were observed for RBM15B, WTAP, FTO, YTHDF2, YTHDF3, IGF2BP2, and IGF2BP3 in glioblastoma samples compared with normal brain controls." (PMID 38398118, 2024). "The overexpression of IGF2BP2 has also been shown to promote the development of glioblastoma multiforme by activating the IGF2/phosphoinositide 3-kinase (PI3K)/Akt pathway, thereby making glioblastoma resistant to temozolomide therapy." (PMID 35919812, 2022). "IGF2BP2 also functions downstream of long noncoding RNA HIF1A-AS2 (hypoxia-inducible factor 1 α-antisense RNA 2), via maintaining HMGA1 expression, and mediates the growth of tumors formed by glioblastoma CSCs." (PMID 29736175, 2018). "In addition, our results showed that the Let-7 target genes (HMGA2, IGF2BP2, and LIN28B) were significantly upregulated in glioblastoma patient-derived cells (GBM04T) after anti-Let-7 treatment." (PMID 27102443, 2016). "Furthermore, HIF1A-AS2 directly binds to insulin-like growth factor 2 mRNA binding protein 2 (IGF2BP2)/ATP-dependent RNA helicase A (DHX9) proteins, resulting in increased expression of HMGA1, formation of glioblastoma stem-like cells, and adaptation to hypoxia in the tumor microenvironment." (PMID 34557530, 2021).
glioblastoma (continued). "In fact, in glioblastoma cells lacking LIN28, let-7 targets have been observed to be protected from miRNA-dependent silencing by the binding of IGF2BP2 to let-7 miRNA responsive elements." (PMID 31484926, 2019).